METTL3 (methyltransferase 3, N6-adenosine-methyltransferase complex catalytic subunit)
Diseases named in the same sentence as METTL3 in open-access papers (continued):
Sharing a sentence is not in itself a finding about the gene and the disease.
Infertility (7 papers, 2017 to 2025). "Using Mettl3 cKO mouse model, we provide evidence in favor that Mettl3 loss causes infertility due to implantation failure." (PMID 37270544, 2023). "Collectively, these results suggested that the reduction of METTL3 might be associated with infertility." (PMID 37270544, 2023). "To investigate the role of m6A and METTL3 in patients with endometriosis-related infertility, we collected mid-secretory endometrial samples from women with endometriosis-related infertility (the ES group)." (PMID 37891533, 2023). "Our novel findings shed new light on the potential of METTL3 as a therapeutic target to enhance cellular decidual function in patients with endometriosis-related infertility and ultimately increase the probability of successful embryo implantation." (PMID 37891533, 2023). "Taken together, these results suggest that the upregulation of METTL3 and m6A probably accounts for the impaired endometrial receptivity in women with endometriosis-related infertility." (PMID 37891533, 2023). "Collectively, this study reveals the role of METTL3-dependent m6A modification in female fertility and provides insight into the pathology of infertility and pregnancy management." (PMID 37270544, 2023). "Conditional deletion of Mettl3 in female reproductive tract by using a Pgr-Cre driver results in infertility due to compromised uterine endometrium receptivity and decidualization." (PMID 37270544, 2023). "Additionally, we attempted to uncover the effect of METTL3 and m6A expression on the decidualization of endometrial stromal cells and the potential mechanisms involved, thereby offering a novel therapeutic approach for improving endometriosis-associated infertility." (PMID 37891533, 2023). "Next, we detected the levels of m6A and METTL3 in the mid-secretory phase of the endometria of infertile women with endometriosis and found that both were expressed at higher levels in the mid-secretory endometria of these women than in those from normal fertile women." (PMID 37891533, 2023). "However, the molecular mechanisms of METTL3 attenuation in the etiology and pathophysiology of infertility remain undetermined." (PMID 37270544, 2023). "Therefore, when m6A and METTL3 levels are increased in stromal cells derived from women with endometriosis-related infertility, cellular decidualization is disrupted, resulting in defective endometrial receptivity." (PMID 37891533, 2023). "In addition, the full extent of METTL3 implication in reproductive diseases, such as EC, infertility, and other disorders, remains largely unknown, and its function and mechanisms are yet to be fully elucidated." (PMID 38332508, 2024). "Taken together, these findings demonstrate that increased METTL3 expression impairs the decidualization of endometrial stromal cells and thus affects embryo implantation, which might largely contribute to endometriosis-related infertility." (PMID 37891533, 2023). "Studies have shown that METTL3-regulated m6A modification facilitates FOXO1 mRNA decay through YTHDF2 in radiation-induced lung injury and endometriosis-related infertility." (PMID 41369154, 2025). "We analyzed the expression of m6A, METTL3, and forkhead box O1 (FOXO1) in ESCs from normal fertile women (the ND group) or women with endometriosis-related infertility (the ED group)." (PMID 37891533, 2023). "In summary, we revealed that METTL3-mediated m6A disrupts the cellular decidual process by promoting the YTHDF2-dependent decay of FOXO1 mRNA, thereby contributing to defective endometrial receptivity in infertile women with endometriosis." (PMID 37891533, 2023). "The findings of the present study indicate that METTL3-mediated m6A modification impairs the decidualization of endometrial stromal cells by promoting YTHDF2-dependent degradation of FOXO1 mRNA, thus affecting embryo implantation and resulting in endometriosis-related infertility to a large extent." (PMID 37891533, 2023).
oral cancer (7 papers, 2020 to 2025). "Here, METTL3, in cooperation with the m6A reader IGF2BP1, enhanced the translation of BMI1 in oral cancer cells, which is thought to underlie the observed cellular phenotypes upon METTL3 depletion or overexpression, although this remains to be formally proven." (PMID 32957697, 2020). "Using in vitro and in vivo models, the biological roles of METTL3 in arecoline-transformed oral cancer were examined." (PMID 36429032, 2022). "Nevertheless, the m6A pathway and its catalytic components, e.g., METTL3, represent interesting and druggable targets to altered RNA metabolism in oral cancer cells." (PMID 32957697, 2020). "The upregulation of METTL3 in oral cancer was also seen in two additional studies that also report a correlation of METTL3 expression with poor prognosis of OSCC patients." (PMID 32957697, 2020). "Furthermore, the crosstalk between METTL3-dependent changes in epitranscriptome and their impact on the epigenetic modifications found in the oral cancer genome, including a potentially altered chromatin organization, need to be analyzed in more detail in the future." (PMID 32957697, 2020). "METTL3, a m6A writer, enhances c-MYC stability by modifying m6A levels in oral carcinoma, whereas YTHDF2, a m6A reader, promotes its degradation." (PMID 41167308, 2025). "Collectively, we discovered that METTL3 was considerably elevated in OSCC of patients with areca nut chewing history and in chronic arecoline-transformed oral cancer cell lines." (PMID 36429032, 2022). "Thus, by controlling METTL3/HIF-1/MYC signaling in oral cancer, our investigations reveal a previously unidentified connection between arecoline and cisplatin resistance that may help develop strategies to overcome the challenge of cisplatin resistance in OSCC patients." (PMID 36429032, 2022). "The METTL3/SALL4 axis, which activates the Wnt/β-catenin pathway post-radiation therapy, enhances the CSC phenotype and leads to radio-resistance in oral cancer, representing a potential therapeutic target to eliminate radio-resistant oral cancer cells." (PMID 39200273, 2024). "Inhibitors targeting pathways regulating OCSC properties, such as the METTL3/SALL4 axis, which activates the Wnt/β-catenin pathway post-radiation therapy, are being tested in preclinical trials and offer promising avenues for potentially curative oral cancer therapies." (PMID 39200273, 2024).
small cell lung carcinoma (7 papers, 2023 to 2025). Small cell lung cancer (SCLC) is a highly aggressive malignant neoplasm, accounting for 10-15% of lung cancer cases, characterized byrapid growth, and early metastasis. "The m6A methyltransferase METTL3 contributes to chemoresistance in small cell lung cancer by activating PINK1-PRKN-mediated mitophagy." (PMID 40855568, 2025). "There are some excellent research results; m6a methyltransferase METTL3 leads to drug resistance in small-cell lung cancer by targeting the mitochondrial autophagy pathway." (PMID 39144972, 2024). "METTL3 induces m6A methylation by promotes mitochondrial autophagy through the Pink1-Parkin pathway, leading to chemotherapy resistance in small cell lung cancer." (PMID 39010105, 2024). "Besides, m6A methyltransferase METTL3 acts as a marker for poor small cell lung cancer prognosis, and it is highly expressed in chemoresistant small cell lung cancer cells." (PMID 38992016, 2024).
acute coronary syndrome (6 papers, 2021 to 2024). Signs and symptoms related to acute ischemia of the myocardium secondary to coronary artery disease. "A previous study investigated how interferon regulatory factor-1 (IRF-1) facilitates macrophage scorching among patients with acute coronary syndrome, and elevated m6A and METTL3 levels were observed in macrophages." (PMID 38562618, 2024). "For example, METTL3 elevates m6A levels of hsa_circ_0029589 and decreases its expression, which promotes macrophage pyroptosis in acute coronary syndrome." (PMID 38383479, 2024). "The overexpression of IRF-1 can induce an increase in the levels of m6A and METTL3 to promote acute coronary syndrome." (PMID 35141221, 2022). "Previous study investigated the manner by which interferon regulatory factor-1 (IRF-1) can promote the pyroptosis of macrophages in patients with acute coronary syndrome and detected increased levels of m6A and METTL3 in the macrophages." (PMID 35141221, 2022). "IRF-1 overexpression increases m6A and METTL3 levels and promotes acute coronary syndrome." (PMID 38562618, 2024).
cervical squamous cell carcinoma (6 papers, 2020 to 2024). A squamous cell carcinoma arising from the cervical epithelium. "When any of the m6A readers (IGF2BP2 and IGF2BP3) or m6A writer METTL3 were mutated, BRD9 was significantly highly expressed in cervical squamous cell carcinoma and endocervical adenocarcinoma (CESC), BRCA and LUAD." (PMID 38303608, 2024). "In cervical squamous cell carcinoma (CESC), ICOS, KIR2DL4, TNFSF9, and CD86 function in immune activation and display a negative association with METTL3 expression." (PMID 39199429, 2024).
COVID-19 (6 papers, 2022 to 2025). A disease caused by infection with severe acute respiratory syndrome coronavirus 2. "Some of DEGs may be associated with the varying severity of COVID-19, such as METTL3, FTO, and RBM15." (PMID 35655464, 2022). "Research has found that, compared to a control group, serum levels of PARC/CCL18 and GNLY (granulysin), as well as IgG levels against MX1 and METTL3, are elevated in patients with AA related to the COVID-19 vaccine." (PMID 39021569, 2024). "COVID-19 patients with high expression levels of FTO tend to display high levels of METTL3, METTL16, RBM15B, or VIRMA." (PMID 35655464, 2022). "Targeting N6-methyladenosine (m6A) pathways (e.g., METTL3/SERPINA1 axis) to restrict SARS-CoV-2 reproduction has therapeutic potential for COVID-19 patients." (PMID 36555339, 2022). "Thus, downregulation of salivary METTL3 and concomitant plaque index reduction characterize the late convalescent phase of COVID-19." (PMID 40917458, 2025). "We hypothesized that post-COVID-19 recovery induces epigenetic alterations, measurable through salivary methyl-transferase-like 3 (METTL3) expression and clinical-periodontal parameters." (PMID 40917458, 2025). "Decreased levels of METTL3 in parotid tissue and in saliva of COVID-19 convalescents were found." (PMID 40917458, 2025). "We observed that RBM15B, HNRNPA2B1, and VIRMA may be protective factors in the development of COVID-19, and the opposite performance was found in ELAVL1, RBM15, FMR1, IGFBP3, and METTL3." (PMID 35655464, 2022).
gastric adenocarcinoma (6 papers, 2021 to 2026). "Our work refined the understanding of METTL3-involved m6A signaling and injected new insights into the field of stomach adenocarcinoma research." (PMID 37344779, 2023). "We continued to focus on the contribution of METTL3 to stomach adenocarcinoma cell growth in vivo." (PMID 37344779, 2023). "To explore the correlation between METTL3 and DNA repair pathways, we analyzed publicly available data from TCGA-STAD (The Cancer Genome Atlas-Stomach Adenocarcinoma) and found a significant positive correlation between METTL3 expression and the DNA repair pathway." (PMID 37822880, 2023). "The discovery of the METTL3-ANGPTL3 axis and its effect on STAD tumor growth will contribute to further studies on the mechanisms of gastric adenocarcinoma development." (PMID 37344779, 2023). "Elucidation of the METTL3-ANGPTL3 axis and its impact on STAD tumor growth will enhance our understanding of the mechanisms underlying gastric adenocarcinoma development." (PMID 41312360, 2025).
hypopharyngeal squamous cell carcinoma (6 papers, 2021 to 2025). "METTL3 mediated the m6A methylation stabilizes circCUX1, which further promoted tolerance to radiotherapy in hypopharyngeal squamous cell carcinoma." (PMID 39143552, 2024). "Research has revealed that methyltransferase like 3 (METTL3) was related to m6A of circCUX1 in Hypopharyngeal squamous cell carcinoma (HPSCC), which was favorable for circCUX1 expression." (PMID 35372031, 2022).
kidney cancer (6 papers, 2020 to 2023). Primary or metastatic malignant neoplasm involving the kidney. "Like METTL3, patients with kidney cancer are more predisposed to METTL14 mutations or CNV, and patients affected by shallow deletions of METTL14 have a poorer OS and DFS." (PMID 32765970, 2020). "Analysis of methyltransferases in kidney cancer, including ccRCC, indicates that both METTL3 and METTL14 are tumor suppressors in this disease." (PMID 32765970, 2020). "Therefore, METTL3 is required for kidney cancer progression in an m6A methyltransferase-dependent manner." (PMID 34631715, 2021). "In our study, we revealed an important role of METTL3 in regulation of kidney cancer progression." (PMID 34631715, 2021). "It has been reported that kidney cancer tissues display a low expression of METTL3 that not only promotes the proliferation, growth, and colony formation of the cancer cells via the PI3K/Akt/mTOR pathway but also activates the EMT to facilitate the migration and invasion of the cells." (PMID 33061938, 2020).
lipid metabolism disorder (6 papers, 2021 to 2025). "Mechanistically, loss of Mettl3 significantly downregulated the expression levels of multiple m6A-modified mRNAs related to lipid metabolism, including Adh7, Cpt1a, and Cyp7a1, further promoting lipid metabolism disorders and liver injury in mice." (PMID 37335109, 2023). "In obese mice, m6A methylation and METTL3 expression were reduced, but after elevating METTL3 level led to an increase in PPARα mRNA level which alleviated lipid metabolism disorders." (PMID 40662138, 2025). "The resveratrol alleviated lipid metabolism disorder under HDF by increasing methyltransferase-like 3 (METTL3) expression and decreasing the level of YTHDF3 and m6A abundance." (PMID 34179148, 2021).
renal carcinoma (6 papers, 2017 to 2024). A carcinoma arising from the epithelium of the renal parenchyma or the renal pelvis. "In renal cancer cells, overexpression of METTL3 leads to decreased PI3K/AKT activation as well as suppressed tumor growth, suggesting a PI3K/Akt-dependent regulatory function of m6A modification in ccRCC." (PMID 38618952, 2024). "If the METTL3/AKT/mTOR signalling exists in renal cancer as well, the patients with overexpressed METTL3 might benefit more from everolimus." (PMID 36162823, 2023). "However, another study of renal cancer confirmed that the mutation frequency of the m6A regulator YTHDC2 was 55.11% and that of METTL3 was 30.11%." (PMID 33926554, 2021).
squamous cell carcinoma (6 papers, 2020 to 2024). A carcinoma arising from squamous epithelial cells. "The main finding of this study was that HPV vaccine treatment of squamous carcinoma is correlated with METTL3 expression and also inhibited the formation of an immunosuppressive tumor microenvironment." (PMID 38030537, 2024). "In this research, through the GEPIA database, we found that high METTL3 expression has a correlation with poor prognosis of squamous cell carcinoma of head and neck." (PMID 34476262, 2021). "In our study, bioanalysis displayed that METTL3 has close relevance with the prognosis of squamous cell carcinoma of head and neck." (PMID 34476262, 2021). "Therefore, the authors conclude that the HPV vaccine inhibits the development of squamous carcinoma by down-regulating METTL3, probably because the downregulation of METTL3 expression increases the sensitivity of tumor cells to cytokines." (PMID 38030537, 2024). "This hypothesis is supported by an observation that METTL3 is elevated and plays an oncogenic role in a variety of squamous cell carcinoma from various organs." (PMID 32216017, 2020).
acute lymphoblastic leukemia (5 papers, 2019 to 2023). Leukemia with an acute onset, characterized by the presence of lymphoblasts in the bone marrow and the peripheral blood. "This study was aimed to explore the METTL3 and METTL14 expressions in children with ETV6/RUNX1(E/R)‐positive acute lymphoblastic leukemia (ALL) and investigate the relation between the METTL3 and METTL14 expressions with clinical features." (PMID 31429529, 2019). "METTL3 and METTL14 expression was reported to be downregulated in pediatric acute lymphoblastic leukemia (ALL) with ETV6/RUNX1 gene rearrangement." (PMID 33922187, 2021).